LY6H (lymphocyte antigen 6 family member H)
Description:
Believed to act as a modulator of nicotinic acetylcholine receptors (nAChRs) activity. In vitro inhibits alpha-3:beta-4-containing nAChRs maximum response. May play a role in the intracellular trafficking of alpha-7-containing nAChRs and may inhibit their expression at the cell surface. Seems to inhibit alpha-7/CHRNA7 signaling in hippocampal neurons.
Synonyms: NMLY6
Tractability: Antibody: its Gene Ontology location is reachable by antibodies, with high confidence; UniProt places it where antibodies can reach, with medium confidence; UniProt predicts a signal peptide or a membrane-spanning region. PROTAC: its protein half-life has been measured.
Gene: Protein-coding gene on chromosome 8 (143,157,914 to 143,160,711, reverse strand). Ensembl gene ENSG00000176956.
Subcellular location: Cell membrane
Pathways (Reactome):
Metabolism of proteins: Post-translational modification: synthesis of GPI-anchored proteins
Gene Ontology:
Molecular function: protein binding; acetylcholine receptor binding; acetylcholine receptor inhibitor activity
Biological process: acetylcholine receptor signaling pathway; animal organ morphogenesis; nervous system development
Cellular component: extracellular region; plasma membrane; synapse
Genetic constraint (gnomAD): Loss-of-function variants: 10 observed, 15.22 expected, observed/expected ratio (o/e) 0.66, 90% interval 0.4 to 1.12. The synonymous counts are far from expectation, so gnomAD's model fits this gene poorly and the ratio says little. Missense variants: 196 observed, 195.37 expected, observed/expected ratio (o/e) 1, 90% interval 0.89 to 1.13. Synonymous variants: 115 observed, 88.05 expected, observed/expected ratio (o/e) 1.31, 90% interval 1.12 to 1.52.
Homologues: Orthologues: chimpanzee LY6H (100% identical), macaque LY6H (98% identical), pig LY6H (90% identical), mouse Ly6h (89% identical), dog LY6H (87% identical), guinea pig LY6H (73% identical). Paralogues in human: LY6S (29% identical), LY6L (25% identical).